CXCL12 (C-X-C motif chemokine ligand 12)
Diseases named in the same sentence as CXCL12 in open-access papers (continued):
Sharing a sentence is not in itself a finding about the gene and the disease.
tumor (continued). "In the current study, we further defined the mechanisms involved in B cell-mediated killing of tumor cells and found that activated B effector cells killed tumor involving the CXCR4/CXCL12 and perforin pathways as well as the Fas/FasL interaction, and can be augmented by IL-2." (PMID 27528023, 2016). "CXCR4-positive tumor cells migrate toward distant organs in response to a CXCL12 gradient." (PMID 25605248, 2015). "Our study not only indicates a pathogenesis for PCa PNI, but also provides evidence that CXCL12/CXCR4 axis might be a novel therapeutic target to prevent tumor perineural dissemination in PCa." (PMID 25605248, 2015). "In particular, the endocytosis induced by CXCL12 has been demonstrated in tumor cells." (PMID 26161302, 2015). "Furthermore, CAFs have been shown to directly enhance tumor angiogenesis by either recruiting endothelial progenitor cells via their secretion of SDF-1/CXCL12 or secreting proangiogenic factors." (PMID 26501341, 2015). "Moreover, single spinal administration of CXCL12 neutralizing antibody reversed the pain hypersensitivity induced by tumor cell implantation." (PMID 25789329, 2015). "Mechanically, TAMs are generally recruited from blood monocytes by diverse chemokines such as CCL2 (MCP-1), CCL5, CCL7, CXCL8 and CXCL12, migrate to diverse areas of the tumor microenvironment and differentiate according to surrounding cellular or environmental stimuli." (PMID 25685069, 2015). "Hence, CXCR4 and CXCL12 form an important signaling axis between tumor cells and their microenvironment, with the interaction influencing the adhesion, migration and invasion of tumor cells, reflecting the strong association of CXCR4 with cancer metastasis." (PMID 25669980, 2015). "Consequently, this observation implies that CXCR4-expressing tumor cells are directed along a cytokine gradient to CXCL12-expressing organs to form metastasis." (PMID 26091099, 2015). "As CXCR4 is expressed in cells in multiple organs including lymph nodes, lungs, and liver, epithelial tumor cells may take advantage of the principle of homing mechanisms to direct the metastasis of CXCL12-positive tumor cells to CXCR4 positive organs." (PMID 25806371, 2015). "These novel oncogenic mechanisms, in addition to the dissemination of CXCR4+ tumor cells to distant lymphatic tissues with high CXCL12 concentrations, may synergistically account for the CXCR4-mediated disease progression." (PMID 25704881, 2015). "Phosphoinositide 3-kinase (PI3K) and mitogen-activated protein kinase (MAPK) pathways have been found to critically affect tumor cell survival and migration, and are important downstream pathways involved in CXCL12/CXCR4 interactions, as summarized in our previous study." (PMID 25997540, 2015). "Indeed, the area of hypoxia was significantly increased and the CXCL12 expression was confirmed to be significantly upregulated in the bevacizumab-treated Y-MESO-14 tumours compared with the control tumours." (PMID 26635184, 2015). "An in-depth research for the role of CXCR7, especially regarding the mechanisms that alter overall availability, distribution and gradients of CXCL12 in tumor microenvironments to regulate the invasion and metastasis of CXCR4 expressing cells, is imperative in the future." (PMID 25605248, 2015). "Furthermore, these cells have increased exposure to the factors necessary for tumor relapse, including CXCL12, through its receptors CXCR4 and CXCR7, IL6 through the Jak2/Stat3 pathway, EGF, FGF and IGF, among others." (PMID 25797268, 2015). "Indeed, CXCR4 is widely expressed on tumor cells, and the preferential sites of metastases, such as bone, liver, and lung, express high levels of its ligand, CXCL12." (PMID 25897429, 2015). "Moreover, CXCR4-expressing tumor cells migrate along the CXCL12 gradient derived from nerves, eventually leading to metastatic spread along the alternative route establishing PNI." (PMID 25605248, 2015).
tumor (continued). "Thus, contribution of CXCR7 within tumor environment has introduced a new level of complexity to CXCL12 signaling." (PMID 25955316, 2015). "As a critical mediator of tumor–stroma interactions, CXCL12/CXCR4 axis plays an important role in the bidirectional tumor-stromal interaction, and therefore may be a promising prognostic marker and therapeutic target in PDAC." (PMID 25679210, 2015). "Indeed, GBM growth and recurrence relies on CSCs that are responsible for tumor vessel formation and bidirectionally interact with tumor ECs via secreted factors, including CXCL12, to preserve stemness and promote self-renewal." (PMID 24904289, 2014). "Moreover, CAFs present in various types of cancer produce CXCL12, and the produced CXCL12 promotes the angiogenic, proliferative, and migratory properties of tumor cells." (PMID 24966464, 2014). "Other studies report that expression of CCL2 and CXCL12 may originate from stromal cells and regulate tumor cell behavior through promotion of paracrine signaling." (PMID 24970800, 2014). "As tumor invasiveness couples with the migratory ability of cells, we first investigated the effect of these drugs on actin polymerization and cell chemotaxis in response to CXCL12." (PMID 25216518, 2014). "Also, secretion of CXCL12 by stromal cells outside of the tumor microenvironment attracts cancer cells via their upregulated CXCR4 receptor." (PMID 26932379, 2014). "Tumor-associated macrophages (TAMs) are derived mostly from circulating monocytes which are attracted into tumor sites by locally produced chemotactic factors, such as CCL2, CCL5, CCL7, CCL8, and CXCL12, and macrophage colony stimulating factor (M-CSF)." (PMID 24966464, 2014). "Importantly, re-introduction of CXCL12 resulted in a marked improvement in survival of tumor-bearing mice." (PMID 24594697, 2014). "As a more direct corollary to clinical samples, xenograft MDA-MB-231 tumors from SCID mice were explanted and cultured on aligned nanofiber arrays, where quantitative assessment of tumor cell migration displayed significant increases in total and net migration in the presence of a CXCL12 gradient." (PMID 25385001, 2014). "Thus, the correlation of CXCR4 and CXCL12 expression levels and tumor invasiveness was proposed to be exploited as potential early diagnostic biomarkers, one of the major challenges in diagnosis and treatment of invasive tumors." (PMID 25484899, 2014). "The direct effect of CXCL12/CXCR4 in tumor metastasis is that CXCL12 increases CXCR4-mediated motility, and the cell surface expression of integrins is mediated by the phosphorylation of extracellular signal regulated kinase (ERK) and downstream activation of the IKKαβ/NFκβ/RELA signaling." (PMID 24944647, 2014). "In addition, tumours with organ secondaries were associated with less methylation of cadherin 13 gene, CDH13, and CXCL12." (PMID 25052224, 2014). "In contrast, a marked attenuation of tumor metastases was observed, suggesting that the CXCL12/SDF-1α and CXCR4 may regulate metastases in an angiogenesis-independent manner." (PMID 24971349, 2014). "In particular, knocking down CXCR4 using RNAi or inhibiting CXCR4 function by AMD3100 in CSCs, impairs proliferation in vivo, effectively reducing tumor growth in two different xenograft models; similarly shRNA CXCL12 knock-down in CSCs inhibited tumor growth in vivo." (PMID 24904289, 2014). "Previous study also showed that tumor cells express a high level of CXCR4 and that tumor metastasis target tissues (lung, liver, and bone) express high levels of the ligand CXCL12, allowing tumor cells to directionally migrate to target organs via a CXCL12-CXCR4 chemotactic gradient." (PMID 24810923, 2014). "The CXCL12/CXCR4 loop may stimulate tumor cell proliferation and induce extracellular matrix rearrangement, necessary for metastasis formation." (PMID 24944647, 2014).
tumor (continued). "Recently it has been shown that tumor cells with high levels of CXCR4 expression orientation migrate to organ sites with high levels of CXCL12/SDF-1 secretion, which suggests that this molecular pair plays a key role in chemotaxis and homing of metastatic cells." (PMID 24941119, 2014). "In summary, our studies revealed that CXCL12/CXCR7-induced STAT3-mediated pathways may enhance tumor growth by regulating angiogenic and proliferative pathways." (PMID 24886617, 2014). "Notably, most CXCL12-positive cells also express CXCR4 strongly suggesting an autocrine/paracrine regulation of tumor cell proliferation." (PMID 25484899, 2014). "In addition, normal cells forming tumor stroma (i.e., macrophages, lymphocytes, fibroblasts, and endothelial cells) concur to cancer development and progression through CXCL12 secretion." (PMID 25484899, 2014). "Thus while a growing body of evidence suggests a tumor-suppressive role for CXCL12 in human cancer malignancy, its mechanistic roles in PDAC remain poorly understood." (PMID 24594697, 2014). "CXCL12 (SDF-1) and CXCL13 (BLC) and their respective receptors CXCR4 and CXCR5 have been implicated in tumor growth, metastasis, and are critical for the regulation of the tumor microenvironment in multiple cancer sub-types as a component of the tumor “Immunome”." (PMID 24795716, 2014). "Thus, CXCL12 drives angiogenesis either directly or in a paracrine manner, supporting tumor growth and GBM cell migration far from hypoxic pseudopalisades, allowing for both necrotic area formation and peripheral invasiveness of GBM." (PMID 24904289, 2014). "CXCR7 is up-regulated in all pathological conditions in which CXCL12 activity is enhanced, including neoplastic diseases, and contributes to tumor growth, adhesion, survival, angiogenesis, and invasion of breast, lung and prostate carcinomas and promotes tumor development in mice." (PMID 24904289, 2014). "One hypothesis concerning the metastatic process is based on an increasing CXCL12 gradient from the primary tumor to secondary niches at metastatic sites." (PMID 24629239, 2014). "CXCL12 is a chemokine that is thought to regulate the migration of BM-derived cells, facilitating their transmigration through endothelial cell barriers into the tumor microenvironment." (PMID 26932379, 2014). "There are evidences that tumor cells express a high level of CXCR4 and that tumor metastasis target tissues (lung, liver, and bone) express high levels of the ligand CXCL12, allowing tumor cells to directionally migrate to target organs via a CXCL12-CXCR4 chemotactic gradient." (PMID 24810923, 2014). "CXCR4 and CXCL12 recruit monocytes and regulatory T cells (Tregs) into the tumor microenvironment." (PMID 24312199, 2013). "Additionally, in both mouse and human tumor cells with either loss or mutation of PTEN, Akt Inhibitor IV treatment inhibited basal as well as CXCL12-induced invasion." (PMID 23902739, 2013). "Tumor cells expressing CXCR4 metastasize to target organs that express high levels of CXCL12." (PMID 23902739, 2013). "Prostaglandin E2 can induce CXCR4 expression in the myeloid derived suppressor cells (MSDCs), which may be subsequently recruited into the tumor by CXCL12 present in the ascitic fluid." (PMID 24384839, 2013). "While there are likely to be multiple mechanisms for the intercellular signaling between MSCs and tumor cells, the chemokine, CXCL12 has been implicated in MSC chemotaxis and homing to tumors, MSC-mediated stimulation of tumor growth and cellular tissue invasion." (PMID 24064862, 2013). "However, concomitant tumor hypoxia and necrosis are accompanied with increased CXCL12 production and TEM infiltration in mouse mammary tumor models." (PMID 24314323, 2013).
tumor (continued). "The chemokine receptor CXCR4 and its chemokine CXCL12 are involved in normal tissue patterning but also in tumor cell growth and survival as well as in the recruitment of immune and inflammatory cells, as successfully demonstrated using agents that block either CXCL12 or CXCR4." (PMID 23449983, 2013). "Moreover, tumor cells can produce both SDF-1/CXCL12 and ITAC/CXCL11, creating a complex signaling background and making experiments with exogenous chemokine ligand difficult to interpret." (PMID 23894550, 2013). "Because the tumor cells in the xenografts migrated to specific regions of the brain or along anatomical structures, including perivascular, perineuronal, and subependymal regions, we examined these areas for the expression of the chemokine CXCL12." (PMID 23527265, 2013). "The chemokine CXCL12 and its cognate receptor, CXCR4, have been implicated in numerous tumour types where expression promotes tumour growth, angiogenesis, metastasis and suppresses tumour immunity." (PMID 22415233, 2012). "However, the relative contribution of the CXCR4/CXCL12 axis in organ-specific dissemination or/and tumor growth has been strongly debated." (PMID 22916293, 2012). "Similarly to the Neu-YB tumors, CXCL12 overexpression in MTLn3 cells increased the number of macrophages present in the tumor parenchyma approximately twofold (P < 0.005)." (PMID 22314082, 2012). "In these tumours, CXCL12 can have pleiotropic roles in autocrine growth stimulation as a tumour cell chemoattractant and as an endothelial stem cell attractant contributing to tumour vascularisation, and can suppress tumour immunity." (PMID 22415233, 2012). "Moreover, due to the nature of this (bone) tumor, attempts to establish primary tumor cell cultures from therapy-naive biopsies for evaluation of CXCL12-induced proliferation have so far been unsuccessful." (PMID 23249693, 2012). "Although several hypotheses on the role of CXCR7 and its possible interaction with CXCR4 have been proposed in different tumor systems, the functional implication of the global CXCL12/CXCR7/CXCR4 axis in NB remains unknown." (PMID 22916293, 2012). "The binding of CXCL12 to its receptor CXCR4 is thought to induce proliferation of tumour cells." (PMID 22415233, 2012). "Since activation of the CXCL12 pathway may promote cancer cell survival, invasion, and stem and/or tumor-initiating cell phenotype, blocking the CXCR4-CXCL12 pathway may be a valid strategy to target various components in solid tumors." (PMID 22399057, 2012). "The CXCR7/CXCL12 axis has been proposed to induce tumor cell migration in various cancer models." (PMID 22916293, 2012). "Increasing expression of CXCL12 within tumours significantly reduces patient survival (P=0.026)." (PMID 22415233, 2012). "The in vitro results suggested that chemotactic CXCL12/CXCR4-signaling is a crucial determinant of site-specific tumour cell extravasation into the liver that was further analysed using the in vivo model for hepatic tumour cell colonization." (PMID 22253872, 2012). "There are a number of possible mechanisms by which increased CXCL12 expression could enhance tumor invasiveness and malignancy." (PMID 22314082, 2012). "Of the 289 samples, 199 (69%) tumours were positive for CXCL12." (PMID 22415233, 2012). "Thus the inherent defect in Neu-YB tumor cell invasiveness is compensated by increased CXCL12 expression." (PMID 22314082, 2012). "The results of these studies indicate that overexpression of CXCL12 in the tumor microenvironment may alter invasive capacity, as well as the tumor-associated immune cells that are recruited to tumors." (PMID 22314082, 2012). "However, we have demonstrated high levels of CXCL12 expression at the primary site of the tumour to be involved in poor prognosis." (PMID 22415233, 2012).
tumor (continued). "Numerous studies have reported that CXCR4 among all chemokine receptors plays a critical role in tumor invasion and metastasis by interacting with its ligand stromal cell-derived factor-1 (SDF-1 or CXCL12), which is highly expressed in common destination organ sites of metastasis." (PMID 22685650, 2012). "Because there is an EGF-CSF-1R paracrine loop with macrophages inducing tumor cell invasion, we tested whether CXCL12 would act on the Neu-YB tumor cells to increase invasion in an autocrine manner or in a paracrine loop with macrophages." (PMID 22314082, 2012). "The CXCR4/CXCL12 axis has been largely shown to participate in tumor development and progression." (PMID 22916293, 2012). "Because Neu-YB tumor cells have been shown to express more CXCL12 than the other mutants and Neu-NDL, we investigated whether CXCR4 signaling plays a role in EGF-induced in vivo invasion in that tumor." (PMID 22314082, 2012). "Lack of CXCL12 expression within tumours was associated with a 51-month survival advantage for patients when compared with patients whose tumours expressed high levels of CXCL12." (PMID 22415233, 2012). "Recent studies of autocrine CXCL12 signaling have indicated that it can induce the differentiation of monocytes into a distinct population of proangiogenic, immunosuppressive macrophages in the tumor microenvironment." (PMID 22314082, 2012). "We previously showed that CXCL12 orchestrates the recruitment of pre-DC2s and protects them from tumor macrophage IL-10-promoted apoptosis, thereby contributing to the immunosuppressive network within the tumor microenvironment." (PMID 21410972, 2011). "A recent study demonstrated that CXCL12/CXCR4 interactions may also promote early extravasation of liver metastatic epithelial tumor cells which determines a critical step in formation of organ-specific metastases." (PMID 21349176, 2011). "Tumour cells with reduced CXCL12 in their immediate microenvironment may be at an advantage to receive endocrine CXCL12 signals, promoting their migration towards ectopic sources of the CXCR4 ligand." (PMID 21521526, 2011). "In EOC, CXCL12 products (i.e. protein and mRNA) have been detected in tumor cells." (PMID 21410972, 2011). "This is supported by mouse models where metastasis of tumour xenografts to the lung may be inhibited by endogenous CXCL12 expression in the xenografted tumour." (PMID 21521526, 2011). "Since CXCL12 is also known to act as a chemoattractant for MCs, we reasoned that MC migration into the tumor tissues might be the result of an interaction between CXCL12 and CXCR4." (PMID 21949886, 2011). "However, CXCR7 also binds to CXCL12 and has been recently found to enhance lung and breast primary tumor growth, as well as metastasis formation." (PMID 22152016, 2011). "CXCL12 has been widely reported to play a biologically relevant role in tumor growth and spread." (PMID 21410972, 2011). "Given the role of hypoxia in T cell activation, and also specifically in Treg, we hypothesised that Treg recruitment is dependent on both CXCL12 production by tumour cells and hypoxia-induced CXCR4 expression in Treg." (PMID 21521526, 2011). "Meanwhile, CXCR7/CXCL12 modulates tumor cell proliferation and migration." (PMID 22180778, 2011). "CXCL12 expression was confined to the tumor stroma and very weak expression in the surrounding normal tissue could be found." (PMID 21949886, 2011). "Also, blood-bourne chemokines such as CXCL-12 are known to attract tumor cells and contribute to their wide spread within the brain." (PMID 21978494, 2011). "In this study, we set out to assess the potential stimulation by CXCL12 of tumor cell TEM towards other chemokines and whether CXCR7 might be able to regulate such effects." (PMID 21672222, 2011). "CXCR7 expressed on the tumor cells could then scavenge CXCL12, resulting in suppression of the activation of the invasion response." (PMID 22152016, 2011).